NES (nestin)
Diseases named in the same sentence as NES in open-access papers (continued):
Sharing a sentence is not in itself a finding about the gene and the disease.
Atrophy (2 papers, 2024 to 2025). Any weakening or degeneration, especially through lack of use. "Pigaflox/WT; Nestin-Cre mosaic cKO female mice exhibited cerebellar atrophy, motor disturbances, and dendritic branching abnormalities in Purkinje cells." (PMID 39521780, 2024). "Recent work also identified Nestin as a critical regulator of autophagy-dependent ferroptosis in muscle atrophy; Nestin interacts with MAP1LC3B (LC3B), catalyzing its polyubiquitination to inhibit autophagy flux and suppress ferroptosis, whereas Nestin knockout exacerbates atrophy." (PMID 41334559, 2025).
autism (2 papers, 2021 to 2022). Persistent deficits in social interaction and communication and interaction as well as a markedly restricted repertoire of activity and interest as well as repetitive patterns of behavior. "It is of note, that a loss-of-function mutation of Camk2a leads to autism like behavior in mice, which was not the case in Nestin-NXN-/- mice, and agrees with the hypothesis that NXN is a modulator but not essential." (PMID 34198070, 2021).
basal cell carcinoma (2 papers, 2014 to 2019). A carcinoma involving the basal cells. "Adenoid and nodular basal cell carcinoma presented Nestin-positive cells at the invasive margin (IM) of the tumour." (PMID 31065284, 2019). "Nestin, VI intermediate filament protein and marker of precursor cells, is also expressed in the stem cells of the hair follicle and in the endothelial cells; moreover, nestin is expressed in the peritumoral stroma of basal cell carcinomas." (PMID 24959179, 2014). "In previous experiments, the stroma of trichoblastomas contained nestin-positive cells, but the stroma of the nevus sebaceous or basal cell carcinomas was negative for nestin." (PMID 31065284, 2019).
brain cancer (2 papers, 2014 to 2024). A primary or metastatic malignant neoplasm affecting the brain. "Expression of CD133 and nestin was associated with poorer outcomes in many cancers, including brain cancers." (PMID 25580136, 2014).
brain glioma (2 papers, 2017). A malignant glioma that involves the brain. "Thus, CD133 and Nestin are two wildly using markers of brain glioma stem cells." (PMID 28969057, 2017).
carcinoma in situ (2 papers, 2017 to 2024). "Next, we analyzed protein expression of nestin in nomal squamous epithelium, carcinoma in situ, ivasive carcinoma and lymph node metastatic carcinama." (PMID 29029411, 2017). "Here, we demonstrate that the expression of nestin is significantly higher in invasive esophageal carcinoma than in carcinoma in situ." (PMID 29029411, 2017).
cardiac hypertrophy (2 papers, 2024 to 2025). "In this study, we demonstrated the development of cardiac hypertrophy in GFP–nestin mice with progressive UUO duration, which occurred without changes in blood pressure and cardiac chronotropism." (PMID 40869420, 2025). "Our findings confirm nestin involvement in complex changes during myocardial hypertrophy and progressive aging." (PMID 36690826, 2024). "Our findings give evidence of important nestin involvement in the myocardial hypertrophy and progressive aging." (PMID 36690826, 2024). "To summarize, these findings give evidence that occurrence of nestin in some cardiomyocytes is related to the pathological changes in the myocardium including the myocardial hypertrophy." (PMID 36690826, 2024).
cardiomyopathies (2 papers, 2018 to 2025). "Elevated cardiac nestin expression is a recognized feature of various cardiomyopathies and may be involved in myocardial remodeling." (PMID 40869420, 2025). "However, the involvement of nestin-positive cells in the development of various cardiomyopathies caused by renal dysfunction has not been studied previously." (PMID 40869420, 2025).
colitis (2 papers, 2015 to 2023). Inflammation of the colon. "Neoangiogenic processes have been described in experimental colitis 35,45,46 and under fibrotic conditions associated with nestin-positive vascular endothelium 47–49." (PMID 25521239, 2015). "In a murine dextran sulphate sodium (DSS) colitis model, myenteric neurons were derived from nestin cells in a 5-HT4R-dependent manner." (PMID 35794374, 2023).
craniosynostosis (2 papers, 2018 to 2023). Craniosynostosis is defined as the premature fusion of one or more cranial sutures leading to secondary distortion of skull shape resulting in skull deformities with a variable presentation. "Out of seven genes with a high (< 10%) or moderate (< 25%) HI score (NES, CCT3, MEF2D, LAMTOR2, ETV3, SSR2, NTRK1), none of them have been linked to craniosynostosis." (PMID 29845577, 2018).
cyst (2 papers, 2021 to 2024). A sac-like closed membranous structure that may be empty or contain fluid or amorphous material. "The outer layer cells of the small cysts were also positively stained for nestin, and more intense staining was observed in the area where the inner cell cluster was attached to the cyst wall in an unusual pattern." (PMID 38892233, 2024). "The large cysts were weakly stained for nestin, although a part of the scleral side of the large cyst wall was more intensely stained for nestin." (PMID 38892233, 2024).
dementia (2 papers, 2014 to 2020). Loss of intellectual abilities interfering with an individual's social and occupational functions. "These authors used nestin and beta tubulin as markers and found significant reductions in proliferation in the HC of 3 PD patients and 5 PD patients with dementia, which they compared to 3 controls." (PMID 25197578, 2014).
Duchenne muscular dystrophy (2 papers, 2024 to 2025). Duchenne muscular dystrophy (DMD) is a neuromuscular disease characterized by rapidly progressive muscle weakness and wasting due to degeneration of skeletal, smooth and cardiac muscle. "In the murine model of the Duchenne muscular dystrophy (the dystrophin/utrophin-deficient mouse) large clusters of nestin+ striated cells co-expressing cardiac troponin I, desmin and connexin 43, were present in the hearts near the end stage of the disease." (PMID 36690826, 2024). "In a murine model of Duchenne muscular dystrophy, the transplantation of nestin-positive cells into myocardial tissue stimulated the proliferation of endogenous CPCs expressing this marker, thereby preventing the development of dilated cardiomyopathy." (PMID 40869420, 2025).
fibrosarcoma (2 papers, 2015 to 2020). A malignant mesenchymal fibroblastic neoplasm affecting the soft tissue and bone. "Six infantile fibrosarcomas with ETV6-NTRK3 fusion showed variable coexpression of nestin (6/6)/CD10 (4/5)/ S100 protein (3/6)." (PMID 32957984, 2020). "The S100 protein, nestin, and CD10 positivity in infantile fibrosarcoma was also a new finding." (PMID 32957984, 2020). "These infantile fibrosarcomas were diffusely and robustly positive for Trk (100%), S100 protein (50%, 3/6 cases), nestin, CD10 (80%, 4/5 cases), and vimentin (100%), but negative for CD34, SMA, desmin, myogenin, and CD56." (PMID 32957984, 2020).
fibrosis (2 papers, 2023 to 2025). the formation of excess fibrous connective tissue in an organ or tissue in a reparative or reactive process. "Nestin, a type VI intermediate filament protein, is a marker of pulmonary dysfunction and fibrosis as it facilitates TGF-β receptor recycling." (PMID 40181186, 2025).
glaucoma (2 papers, 2020 to 2022). Increased pressure in the eyeball due to obstruction of the outflow of aqueous humor. "The hereby presented study was in fact designed to develop a diagnostic biochip to identify and quantify nestin (together with specific glaucoma proteins) in the aqueous humor obtained from human eyes." (PMID 35789864, 2022). "The IOP has been found associated with upregulated expression of nestin that is an indicator of the retina injury in experimentally induced glaucoma in the glial cells." (PMID 32666339, 2020). "Being the technique fast, user-friendly, and feasible in a clinical setting, it is worthwhile exploring its potential in testing and validating nestin as a clinical biomarker both in the diagnosis and in the progression of glaucoma." (PMID 35789864, 2022). "Nestin is a glia activator involved in neurodegenerative diseases and glaucoma." (PMID 35789864, 2022). "Indeed, the specificity of nestin as glaucoma biomarker depends on its finding in the aqueous humor." (PMID 35789864, 2022). "Therefore, it is not surprising that TM, once affected by any external insult (glaucoma included), will express nestin in detectable amounts both in the tissue and the AH." (PMID 35789864, 2022). "Furthermore, in experimental glaucoma of the rat, elevated IOP induces Müller glial cell activation as manifested by nestin expression." (PMID 35789864, 2022).
GM1 gangliosidosis (2 papers, 2020). A rare lysosomal storage disorder characterized biochemically by deficient beta-galactosidase activity and clinically by a wide range of variable neurovisceral, ophthalmological and dysmorphic features. "To assess the cellular phenotypes present in GM1 gangliosidosis, we first differentiated the disease-derived iPSC lines into NSCs expressing specific markers, SOX1, PAX6, and NESTIN." (PMID 32302553, 2020).
head and neck cancer (2 papers, 2021 to 2023). A primary or metastatic malignant neoplasm affecting the head and neck. "Similarly, others have revealed nestin expression in proliferating vascular endothelial cells near a tumor and in the tumor cells themselves, including in head and neck cancer models." (PMID 37015965, 2023). "Based on the results of recurrence and death, it is our opinion that nestin could be used generally to stratify head and neck cancers." (PMID 33805026, 2021).
hemangioblastoma (2 papers, 2008 to 2024). "Using the MACS method, Scl+ hemangioblastoma-like cells were isolated from multipotent nestin-expressing stem cells." (PMID 39850947, 2024).
hyperplasia (2 papers, 2017 to 2024). An abnormal increase in the number of cells in an organ or a tissue with consequent enlargement. "Victor K’s investigation had identified a population of multipotent stem cells coexisting in human prostate stromal tissue, and our previous study further demonstrated that nestin+ MSCs were recruited by TGF-β in prostatic stromal hyperplasia." (PMID 38711089, 2024).
infarction (2 papers, 2014 to 2024). A localised pathological necrosis of tissue resulting from obstruction of the blood supply usually by a thrombus, an embolus, or vascular torsion. "In those samples, nestin+ cardiomyocytes were located in the vicinity to the necrotic area, in some capillaries growing into the necrotic infarction area and infrequently in some interstitial cells." (PMID 36690826, 2024). "To verify whether pericytes participate in fibrous tissue accumulation after myocardial injury, we induced infarction in Nestin-GFP/NG2-DsRed transgenic mice by ligating the LAD coronary artery." (PMID 25376879, 2014).
injury (2 papers, 2022 to 2024). Damage inflicted on the body as the direct or indirect result of an external force, with or without disruption of structural continuity. "As 4μ8C pretreatment could prevent apoptosis of Nestin-knockout MSCs in vitro, we detected whether IRE1α inhibition could ameliorate MSC apoptosis and enhance the therapeutic effect in an LPS-induced lung injury model." (PMID 39872742, 2022).
leukodystrophies (2 papers, 2016 to 2021). "Based upon BrdU incorporation we have previously shown that TSC1 mobilizes and triggers the proliferation of nestin-expressing progenitors in a rat model of leukodystrophy." (PMID 35558521, 2016). "To determine whether astrocytes in Mcl-1-deleted mice had increased NESTIN expression, as seen in these leukodystrophies, we compared NESTIN+/GFAP+ populations in P14 Mcl-1cKO mice and controls." (PMID 34873168, 2021).
lupus (2 papers, 2018 to 2020). "The correlations among nestin, nephrin and proteinuria were analyzed in LN patients and MRL/lpr lupus-prone mice." (PMID 32371936, 2020). "This is in agreement with our results as we detected Nestin+Sca1+PDGFRα+CD45− MSCs and T cells in the pelvis wall of autoantibody negative lupus-prone mice." (PMID 29777158, 2018).
metastatic disease (2 papers, 2016 to 2017). "A high level of Nestin expression was significantly associated with serous macroscopic vascular invasion (P = 0.002), advanced BCLC stage (P < 0.003) and metastatic disease (P = 0.012)." (PMID 27412382, 2016).
multiple sclerosis (2 papers, 2014 to 2016). A progressive autoimmune disorder affecting the central nervous system resulting in demyelination. "In support of this hypothesis, nestin reexpression has been observed following experimental hippocampal lesions and also in human pathology such as multiple sclerosis." (PMID 27579183, 2016). "In human multiple sclerosis tissue, it was noted than NECs were in close proximity to microglia, and that TGF-β1 expression by microglia upregulated nestin expression." (PMID 24666402, 2014).
myelofibrosis (2 papers, 2021 to 2022). A partial or complete replacement of the bone marrow stroma by fibrous tissue. "As a consequence, nestin-positive MSCs were preserved in bone marrow of VF;IL-1β−/− mice and the presence of nestin-positive MSCs correlated with reduced myelofibrosis." (PMID 36100613, 2022). "Knockout of IL-1β in hematopoietic cells of JAK2-V617F mice reduces inflammatory cytokines, prevents damage to nestin-positive niche cells and reduces megakaryopoiesis, resulting in decrease of myelofibrosis and osteosclerosis." (PMID 36100613, 2022). "In turn, the expression of VEGFR2 correlated with the grade of myelofibrosis (p = 0.001; ρ = 0.53, 95% CI 0.25-0.71) and the presence of nestin-positive stem cell niches (p = 0.001; ρ = 0.53, 95% CI 0.22-0.74)." (PMID 33704530, 2021). "Internal consistency analysis regarding evaluation of the immunohistochemical markers yielded good or excellent results for myelofibrosis, nestin niches, CD34-positive blast counts, and counting of granzyme B, T-bet, FoxP3, CD3, CD4, CD8, and E-cadherin positive cells." (PMID 33704530, 2021). "A link between increase of nestin+ MSCs and reduced myelofibrosis was also found in our clinical phase II trial using Mirabegron, a β−3 sympathomimetic agonist, that corrected the damage inflicted by the MPN clone on the nestin+ MSCs40." (PMID 36100613, 2022).
neuropathy (2 papers, 2016 to 2022). A disorder affecting the nervous system that manifests with pain, tingling, numbness, and/or muscle weakness. "For instance, the R94W mutation is associated with a more severe neuropathy versus the relatively mild one described in patients with the T105M mutation and/or the fact that the Ella-Cre or neuron specific enolose promoter is more, or less, potent compared to our use of the nestin-cre promoter." (PMID 27907123, 2016). "Neuropathy in the skull bone marrow of recipients of VF BM correlated with a significant reduction in Nestin-GFP + MSC numbers, whereas comparable numbers of Nestin-GFP + MSC were observed in recipients of VF;IL-1β-/ and WT bone marrow." (PMID 36100613, 2022).
odontogenic neoplasm (2 papers, 2021 to 2024). A benign or malignant neoplasm arising from tooth-forming tissues. "Previous studies have discussed the expression of nestin as a useful marker for the identification of odontogenic ectomesenchyme and odontoblasts in odontogenic tumours." (PMID 33917771, 2021). "However, in mixed odontogenic tumors, nestin immunoreactivity is evident in the odontogenic ectomesenchyme, particularly in regions adjacent to the odontogenic epithelium." (PMID 38390958, 2024).
oral squamous cell carcinoma (2 papers, 2019 to 2021). "In cases of oral squamous cell carcinoma, the expression of nestin was found to be decreased with the loss of differentiation." (PMID 31675305, 2019). "Nestin expression was increased in samples of leukoplakia and oral squamous cell carcinoma when compared with normal mucosa." (PMID 31675305, 2019). "Western blot and immunohistochemistry analysis were performed to study the expression pattern of nestin in normal mucosa, leukoplakia, and oral squamous cell carcinoma samples." (PMID 31675305, 2019). "Neoangiogenesis status determined by nestin expression showed an increasing expression from normal mucosa through leukoplakia, to oral squamous cell carcinoma." (PMID 31675305, 2019).
osteoarthritis (2 papers, 2021 to 2025). A noninflammatory degenerative joint disease occurring chiefly in older persons, characterized by degeneration of the articular cartilage, hypertrophy of bone at the margins and changes in the synovial membrane. "PTH-induced osteoarthritis pain relief is inhibited by PTH type one receptor knockout on Nestin+ MSCs." (PMID 33646122, 2021). "In addition, the knockout of Tgfbr2 in nestin-positive skeletal progenitors reduced the development of osteoarthritis in an anterior cruciate ligament transection (ACLT) osteoarthritis mouse model." (PMID 40141345, 2025). "To validate the role of PTH-induced remodeling of subchondral bone in the attenuation of osteoarthritis pain and osteoarthritis progression, we induced conditional knockout of PTHIR in Nestin+ MSCs of DMM mice." (PMID 33646122, 2021). "Intermittent PTH attenuated the increases of Nestin+ and Osterix+ cells in subchondral bone marrow of DMM mice, suggesting that early initiation of iPTH attenuates aberrant bone formation in osteoarthritis by modulating the recruitment of osteoprogenitors in subchondral bone." (PMID 33646122, 2021).
osteosclerosis (2 papers, 2018 to 2022). Abnormally high bone density. "The pathogenic role of Nestin-gfp+ cell reduction was uncovered by enforced reduction of these cells using Nestin-creERT2iDTA mice, which aggravates hallmarks of disease, including hematological parameters and osteosclerosis of the bone marrow." (PMID 29541793, 2018).
pancreatitis (2 papers, 2009 to 2025). Inflammation of the pancreas. "Further evidence for a non-fibrotic pancreatitis phenotype in Tgfbr2fspKO mice was demonstrated by the lack of expansion of nestin-positive stellate cells." (PMID 19625278, 2009). "Our results agreed with previous reports that nerves invaded by cancer cells or located in the pancreatitis lesions adjacent to the cancer cells were Nestin-positive, whereas nerves without visible signs of invasion located outside the TME or in the normal pancreas were Nestin-negative." (PMID 40075699, 2025).
Peritoneal Fibrosis (2 papers, 2020 to 2022). Disorder characterized by a wide range of structural changes in PERITONEUM, resulting from fibrogenic or inflammatory processes. "In this study, we aimed to find the role of Nestin in peritoneal fibrosis and the mechanism, thus providing a new target for the treatment of peritoneal fibrosis." (PMID 33391003, 2020). "Our findings contribute to widening our understandings of how Nestin regulates peritoneal fibrosis in these proliferating cells." (PMID 33391003, 2020). "The aim of our study is to demonstrate Nestin’s role in the development of peritoneal fibrosis (PF), and to provide a new target (Nestin) to treat PF." (PMID 33391003, 2020). "In PD mice models, the upregulation of nestin proteins could stimulate peritoneal fibrosis by protecting HIF1-α from proteasomal degradation." (PMID 36101746, 2022).
pituitary tumor (2 papers, 2017 to 2025). A benign or malignant neoplasm affecting the pituitary gland. "In this study, we found higher protein and/or mRNA levels of DPPA4‐associated stem cell factors (SOX‐2, OCT‐4, KLF‐4, SNAIL‐1, and Nestin) in PAE male pituitaries, suggesting that PAE similarly enhances estrogen‐induced pituitary tumor cell stemness in both sexes." (PMID 41017273, 2025).